WDR11 (WD repeat domain 11)
Diseases named in the same sentence as WDR11 in open-access papers (continued):
Sharing a sentence is not in itself a finding about the gene and the disease.
tumor (4 papers, 2017 to 2025). "The genes in the leading edge of the GSEA included Myc, Ccnd1 and Ccnd2, consistent with the delay in tumor development in mice harboring G3 MB overexpressing WDR11." (PMID 29029386, 2017). "Gene set enrichment analysis showed that genes in the KEGG WNT signaling pathways were down-regulated in tumor cells overexpressing WDR11." (PMID 29029386, 2017). "In contrast, enforced expression of WDR11 led to a significant increase in survival of tumor-bearing mice compared to mouse G3 tumorspheres infected with an empty vector (lower right)." (PMID 29029386, 2017). "Specifically, enforced expression of WDR11 led to a 6-day increase in median survival of tumor-bearing mice." (PMID 29029386, 2017). "In conclusion, we demonstrated that common spontaneous mutations were shared between human and murine models of MB suggesting similar molecular mechanisms of tumorigenesis, and identified WDR11 as a protein with tumor suppressive activity in G3 MB." (PMID 29029386, 2017). "Genes in the KEGG WNT signaling pathway, including Ccnd1/2/3, Myc and Tcf7l1, were down-regulated in the transcriptome of G3 MB tumorspheres overexpressing WDR11, consistent with reduced tumor progression." (PMID 29029386, 2017). "In these tumorsphere lines, over-expression of WDR11 gene and protein also resulted in a significant increase in survival of WDR11-expressing tumor-bearing mice compared to controls (p < 0.05)." (PMID 29029386, 2017). "We also identified Wdr11 as a putative tumor suppressor in Group3 MB." (PMID 29029386, 2017). "There were four non-silent mutations in this tumor, all missense SNVs: Lrfn2 R656H, Smyd1 R237Q, Ubn2 Q549K and Wdr11 I46T." (PMID 29029386, 2017). "Over-expression of WDR11 resulted in the down-regulation of WNT signaling pathway and regulators of G1 progression including Myc and D-type cyclins, Ccnd1,2 and 3 consistent with the delay in tumor development and increased survival." (PMID 29029386, 2017). "Indeed, enforced expression of wild-type WDR11 (but not LRFN2, Ubn2, Smyd1) hindered G3 MB development, which is in-line with our hypothesis about its tumor suppressor activity." (PMID 29029386, 2017).
cancer (2 papers, 2021 to 2022). A tumor composed of atypical neoplastic, often pleomorphic cells that invade other tissues. "Consistent with the literature, the results of the present study showed fusion of the FGFR2 gene with nine different partners, namely, TACC2, BICC1, BTBD16, WAC, HFM1, HOOK1, INPP5F, C10orf90, and WDR11, in five different types of cancer." (PMID 35342406, 2022).
cardiovascular disease (1 paper, 2023). "In addition, we identified several interesting candidates such as Taf4b, Tmc8, Wdr11, and Grk5 that were previously associated with different chronic metabolic and inflammatory diseases including T2D, cardiovascular disease, and/or IBD69,70,74,76,77,80,81." (PMID 36788222, 2023).
metabolic disease (1 paper, 2018). A congenital disorder (due to inherited enzyme abnormality) or acquired (due to failure of a metabolically important organ) disorder resulting from an abnormal metabolic process. "Our data show that WDR11 deficiency causes childhood obesity, implicating Hh signalling in metabolic diseases." (PMID 29263200, 2018).
WDR11 also shares sentences with these, for which no sentence is quoted: Anosmia (4 papers); pituitary stalk interruption syndrome (3); coloboma (2); cryptorchidism (2); endocrine disorders (2); Micropenis (2); Anophthalmia (1); autism (1); cardiac diseases (1); congenital hypopituitarism (1); cytomegalovirus infection (1); Delayed puberty (1); infection (1); medulloblastoma (1); microphthalmia (1); neurological disorders (1); Noonan syndrome (1); Nystagmus (1); Optic neuropathy (1); premature ovarian failure (1); renal agenesis (1); uveitis (1).